IL17A (interleukin 17A)
Diseases named in the same sentence as IL17A in open-access papers (continued):
Sharing a sentence is not in itself a finding about the gene and the disease.
psoriasis (continued). "For instance, IL-4 and IL-13, pathogenic for atopic dermatitis, and IL-17A, pathogenic for psoriasis, lead to a downregulation of filaggrin." (PMID 38132754, 2023). "Innate immune cells, such as type 3 innate lymphoid cells, γδT cells, or mucosal-associated invariant T cells, also secrete IL-17A, and are involved in the development of psoriasis." (PMID 37762500, 2023). "The rs2275913 single nucleotide polymorphism (SNP) in the IL17A gene, featuring a substitution of guanine (G) with adenine (A), was linked to an increased risk of psoriasis by enhancing IL17A production and promoting inflammation." (PMID 37569685, 2023). "IL-17A has been implicated in the pathogenesis of many common autoimmune disorders, including MS, as well as rheumatoid arthritis (RA), psoriasis, and inflammatory bowel disease." (PMID 36817487, 2023). "Psoriasis is a common chronic inflammatory skin condition caused by abnormalities in the immune system, and IL‐17A produced by skin Th17 cells and keratinocytes is closely linked to the pathogenesis of psoriasis." (PMID 37506139, 2023). "Th17 cells and the powerful cytokine IL-17A produced by these cells play a pivotal role in the pathogenesis of the aberrant immune response in psoriasis, with Notch1 signaling implicated in Th17 cell differentiation and function." (PMID 38239345, 2023). "PD-1–deficient mice exhibit elevated levels of IL-17A from γδ T cells and greater disease severity of imiquimod-driven psoriasis, which accords well with our observations." (PMID 36480166, 2023). "Out of those, differentiated TH17 comprises the central pathogenic cell subtype of psoriasis, orchestrating the expression of IL-17A, IL-17F, and IL-22, amongst others." (PMID 37108251, 2023). "In contrast, low plasma IL-17A levels were associated with an increased incidence of CVD in patients with moderate-to-severe psoriasis." (PMID 38137722, 2023). "This shows that, surprisingly, global CD200R1 deficiency reduces the severity of psoriasis-like skin inflammation due to a reduced IL-17A production." (PMID 36623588, 2023). "Our results also indicate that physicians should use IL-17A inhibitors with caution in patients with psoriasis associated with cardiometabolic disease." (PMID 36902720, 2023). "An increased production of T helper 1 and IL-17A cytokines, which play a central role in the pathogenesis of psoriasis, was associated with leptin." (PMID 37895330, 2023). "TGF-β1 then conditions infiltrating IL-26+ TH17 to mature into IL-17A-producing cells, suggesting a unique tissue control of pathogenic T H17 cells in psoriasis via epithelial crosstalk." (PMID 37391412, 2023). "IL-17A is linked to the pathogenesis of various autoimmune conditions such as psoriasis, MS, IBD, and seronegative SpA, as well as animal models of autoimmunity." (PMID 37833861, 2023). "But as IL-17F does not only contribute to psoriasis, but also to mucosal immunity, the blockade of IL-17F along with IL-17A results in an increased risk for candida infections." (PMID 37283755, 2023). "As an illustration, ixekizumab, Risankizumab, secukinumab, and guselkumab selectively target interleukin-17A (IL-17A), a protein that is pivotal in the inflammatory mechanism underlying psoriasis." (PMID 38222196, 2023). "The production of IL-17A and IL-22, key inflammatory cytokines that are heavily implicated in the pathogenic of psoriasis, by CD4+ T cells has marked CD4+ T cells as a main target of research." (PMID 38067173, 2023). "Serum levels of IL-17A are increased, which increases are implicated in the pathogenesis of psoriasis." (PMID 36982727, 2023). "The pathogenesis of psoriasis predominantly involves epidermal hyperkeratosis associated with dysregulation of interleukin (IL)-17A-mediated immune responses in inflamed skin lesions." (PMID 35457132, 2022). "Clinical research shows that the treatment of psoriasis with IL-17A inhibitors also reduces cardiovascular risk in patients with psoriasis." (PMID 35514987, 2022).
psoriasis (continued). "IL-17A is the main factor causing skin pathology in psoriasis patients, and serum beta defensin-2 is a simple-to-measure biomarker of IL-17A-driven skin pathology." (PMID 36557635, 2022). "For example, in patients with IBD, frequently associated with psoriasis, the use of IL‐17A inhibitors is usually considered improper." (PMID 35959523, 2022). "This study aimed to estimate serum IL-17A and Claudin-1 levels, investigate their correlation, and evaluate their diagnostic significance as potential blood-based biomarkers in psoriasis." (PMID 35340911, 2022). "IL-17A, the major downstream cytokine of IL-23, is most strongly implicated and well-studied in psoriasis pathogenesis." (PMID 35075118, 2022). "Recent scRNA-seq data showed that the T17 cell subset that most conforms to current concepts of pathogenic Type 17 T-cells in human psoriasis skin was the IL-17A+ IFNγ+ T17 cell subset, synthesizing high levels of TNF, IL-26 and IL-36G." (PMID 36110854, 2022). "On the other hand, other traditional drugs, such as methotrexate, have neutral effect on the cardiovascular risk in psoriasis, whereas biologic agents, such as IL-17A inhibitors, result in improvement of arterial and myocardial function." (PMID 35215285, 2022). "Reminiscent of IL‐17A, IL‐17F was also found to be associated with IκBζ‐mediated regulation of psoriasis‐associated genes in cultured human keratinocytes." (PMID 36245291, 2022). "In our study, S100A7, S100A8 and S100A9 were significantly involved in the IL-17A pathway, which is strongly implicated in psoriasis pathogenesis." (PMID 36483564, 2022). "Psoriasis is a T cell mediated disease involving Th17 cells secreting interleukin (IL)-17A and IL-22 which are proinflammatory cytokines that causes proliferation of keratinocyte (KC) and activation of synoviocyte." (PMID 35625774, 2022). "IL-17A is associated with the histopathological features of psoriasis, such as epidermal hyperplasia and intraepidermal neutrophil micro-abscess." (PMID 35371044, 2022). "In summary, our finding suggested that the levels of circulating bioactive IL-17A were associated with disease activity in psoriasis patients." (PMID 36118416, 2022). "IL-17A is also intimately implicated in the development of TNF-driven autoimmune disorders such as psoriasis, spondyloarthritis and Crohn’s disease." (PMID 36396641, 2022). "First, psoriasis has received much attention in recent years, since maternal psoriasis is also a significant risk factor for ASD, and IL-17A is one of the most important cytokines in the pathogenesis of psoriasis." (PMID 35211045, 2022). "The role of E138A mutation in inducing psoriasis pathogenicity by up-regulating IL-17A has been reported." (PMID 36012602, 2022). "Taken together, these findings highlight the essential standing point of IL-17A-producing TRM as one of the pathogenic populations of skin TRM in psoriasis." (PMID 34501272, 2021). "Monocytes stimulated by LPCs can produce IL-1β to further activate T lymphocytes to secrete IL-17A, which is an important pathogenic factor in psoriasis." (PMID 33602246, 2021). "It has been observed that epidermal expression of STAT3 in a transgenic mouse, activated by the IFN-γ, IL-6, IL-20, IL-17A, and IL-22 cytokines, causes psoriasis." (PMID 34769005, 2021). "IκBζ, a mediator of IL17-A-induced transcriptome activity, is known as a key regulator of specific psoriasis-associated genes that include DEFB4, S100A7, and IL-16." (PMID 34445513, 2021). "It is well-known that the interaction between IL-17A and keratinocyte causes the pathogenesis of psoriasis." (PMID 34955833, 2021). "IL-17A is also involved in angiogenesis, another hallmark of psoriasis, as it is a known pro-angiogenic factor able to stimulate migration of endothelial cells as well as expression of VEGF." (PMID 34201664, 2021). "In contrast, psoriasis is associated with Th17 T-cells producing Th17 cytokines such as IL17A and IL22." (PMID 34445339, 2021).
psoriasis (continued). "IL-17A has also been implicated as a pathogenicity factor in a number of chronic inflammatory diseases, including multiple sclerosis, arthritis, and psoriasis." (PMID 34573058, 2021). "The IFN-γ, IL-17A and IL-22 are key pathogenic cytokines in psoriasis and one of the main mediators of cytokine signaling is STAT1." (PMID 33986690, 2021). "Psoriasis-like keratinocytes were generated by treating human primary keratinocytes with the psoriasis-associated cytokines IL-17A, TNF-α and IL-22." (PMID 33801280, 2021). "On the contrary, coexpression of IL-22 and IL-17A has been implicated in the development of proinflammatory processes during inflammatory and autoimmune diseases, such as psoriasis and Crohn's disease." (PMID 34805416, 2021). "Persistently elevated IL-17A/F levels are also associated with several autoimmune diseases, including psoriasis, rheumatoid arthritis, and Crohn’s disease." (PMID 33824206, 2021). "And we also analyzed the recovery status and pathogenic cytokines (e.g., IL-17A) in mouse psoriasiform models that were transplanted with fecal microbiota from patients with psoriasis or healthy controls." (PMID 34881280, 2021). "Genes involved in angiogenesis and blood vessel development pathways, which are associated with psoriasis, are significantly upregulated by the combination of IL-17A + IL-36γ, and to a lesser extent in response to IL-36γ alone." (PMID 34440590, 2021). "As a result, IL-17A has been the subject of much research as a major causative cytokine in the pathogenesis of psoriasis." (PMID 34445513, 2021). "For example, NK cells are mainly responsible for CHS; ILC2s contribute more to the pathogenesis of AD; ILC3s are the major source of IL-17A, causing psoriasis." (PMID 34831296, 2021). "In support of a pathogenic role for these cells in the skin, IL-17A producing RORγt+ ILCs have been implicated in models of psoriasis." (PMID 34699567, 2021). "The psoriasis-associated cytokines IL-17A, IL-22 and IFN-γ induce the expression of the transcription factor Nrf2 and subsequently KRT17, eventually leading to hyperproliferation of keratinocytes." (PMID 33801280, 2021). "Psoriasis is a common chronic inflammatory skin disease associated with overproduction of interleukin-17A (IL-17A)." (PMID 33602246, 2021). "Adiponectin-deficient mice suffer from severe psoriasis-like skin inflammation and increased infiltration of IL-17 secreting skin Vγ4 γ δ-T cells, particularly upregulation of the Th17-related cytokines IL-17A, IL-17F and IL-22." (PMID 34372872, 2021). "First, we studied circulating T cells producing the psoriasis hallmark cytokine IL-17A alongside IL-10 producing T regulatory (Treg) in psoriasis patients and HV." (PMID 34362923, 2021). "Psoriasis is a major inflammatory skin disease in which the interaction between IL-17A and epidermal keratinocytes plays a critical pathogenic role." (PMID 32070069, 2020). "KLK-7, a serine protease involved in skin barrier functions, displayed a similar disease- and pharmacodynamic- relevance as IL-17A, prompting the consideration of its causal role in psoriasis manifestation and apremilast efficacy." (PMID 31953524, 2020). "A causal role for IL-17A-dependent inflammation in driving psoriasis is highlighted by the success of monoclonal antibody-based therapies that bind IL-17A and block signaling through the IL-17A receptor." (PMID 33301461, 2020). "K17 expression expressed aberrantly in the suprabasal keratinocytes, which is regarded as a hallmark of psoriasis that is primarily induced by IL-17A through STAT3 and ERK1/2, thus promoting the proliferation of keratinocytes and T cells." (PMID 31924750, 2020). "Authors suggested that IL-17A is associated with EI psoriasis that has a recent onset, is quickly spreading, shows guttate morphology, and is often associated with severe pruritus and pustule formation." (PMID 32587472, 2020).
psoriasis (continued). "A phase 2 clinical trial has shown that inhibitory treatment of IL-17A is effective, indicating the pathogenic role of IL-17A in mediating important inflammatory pathways in psoriasis." (PMID 33132897, 2020). "Epidermal keratinocytes represent a rich source of C-C motif chemokine 20 (CCL20) and recruit CCR6+ interleukin (IL)-17A–producing T cells that are known to be pathogenic for psoriasis." (PMID 31936670, 2020). "We now confirm that induction of S100-alarmins in an imiquimod-induced murine model of psoriasis-like skin inflammation was associated with an increased expression of interleukin (IL)-1α, IL-6, IL-17A, or TNFα." (PMID 33643287, 2020). "Keratinocyte-derived OAS2 can be induced by not only IFNβ, but also psoriasis associated cytokines like IL-17A and IL-6." (PMID 32849499, 2020). "In patients with moderate-to-severe psoriasis, treatment with apremilast was associated with significant reductions in plasma levels of interleukin (IL)-17F, IL-17A, IL-22, and TNF-α." (PMID 33178709, 2020). "Positive therapeutic responses to biologics and lesional transcriptomic analysis have highlighted the critical pathogenic role of IL-17A in psoriasis." (PMID 31936670, 2020). "In particular, Secukinumab, a fully humanized anti-IL17A mAb aimed at suppressing pathogenic Th17 and Th1-like Th17 cell subset, has been approved in 2005 as first-line therapy for psoriasis." (PMID 32093011, 2020). "CCL20 produced from IL-17A-stimulated keratinocytes recruits IL-17A-producing Th17 cells and ILC3s and accelerates the feed-forward vicious cycle, which causes fully developed psoriasis." (PMID 32070069, 2020). "Dysregulated expression of IL-17A and IL-17F is associated with chronic inflammatory diseases such as psoriasis, psoriatic arthritis, rheumatoid arthritis, ankylosing spondylitis, and asthma." (PMID 32973785, 2020). "The number of Th17 cells and their associated secreted cytokines including IL-17A, IL-17F, and IL-22 was significantly elevated in the skin lesions and peripheral blood of patients with psoriasis." (PMID 32280718, 2020). "Although the biological implications of increased antimicrobial peptides in psoriasis remain obscure, they are intimately associated with IL-17A-rich milieu." (PMID 32070069, 2020). "The excellent clinical efficacy of anti-interleukin 17A (IL-17A) biologics on psoriasis indicates a crucial pathogenic role of IL-17A in this autoinflammatory skin disease." (PMID 32070069, 2020). "Homozygous CD11c-IL-17Aind/ind mice and heterozygous CD11c-IL-17A ind/+ mice show a delayed onset of moderate to severe psoriasis-like skin disease associated with reduced amounts of cutaneous IL-17A compared with K14-IL-17Aind/+ mice." (PMID 32070069, 2020). "Psoriasis is a chronic skin condition characterized by inflammation and is associated with high serum IL17A." (PMID 32708317, 2020). "The skin lesions showed an increased expression of psoriasis-associated genes such as IL17A, IL22 and DEFB4A." (PMID 32316273, 2020). "IL-17A is associated with the pathogenesis of inflammatory diseases, including psoriasis, atopic dermatitis, hidradenitis suppurativa, alopecia areata, pityriasis rubra pilaris, pemphigus, and systemic sclerosis." (PMID 33281823, 2020). "In the future, for a better management of psoriasis cardiovascular co-morbidities, the association of anti-IL-17A therapy with an anti-IL-36γ treatment should be considered." (PMID 32352958, 2020). "Growing evidence indicated that psoriasis is strongly associated with IL-17A, and clinically, the monoclonal antibodies to IL-17A or its receptor IL-17R showed a dramatic effect against psoriasis." (PMID 32454795, 2020). "Currently, the effects of IL-17A neutralization on psoriasis-associated comorbidities are being investigated." (PMID 32010143, 2019). "IL-17A together with other Th17 cytokines also upregulates the production of several chemokines that are implicated in psoriasis pathogenesis." (PMID 32010143, 2019).
psoriasis (continued). "Interleukin 17A (IL-17A) is one of the currently known six members of the IL-17 cytokine family and is implicated in immune responses to infectious pathogens and in the pathogenesis of inflammatory autoimmune diseases like psoriasis." (PMID 32010143, 2019). "Compared to TNF-α inhibitors, the newer biologics for psoriasis such as anti-IL-12/23 and anti-IL-17A agents are generally considered with a lower risk of active TB or LTBI reactivation." (PMID 31881026, 2019). "Even neutrophils have been implicated as major producers of IL-22 and IL-17A and recent animal models have re-explored their role as effector cells in psoriasis pathophysiology." (PMID 31019502, 2019). "Psoriasis skin manifestations, cardiovascular as well as metabolic disease in psoriasis appear to share pathogenic mechanisms evolving around IL-17A and its proinflammatory role." (PMID 32010143, 2019). "To address these questions, we used mice with a keratinocyte-specific overexpression of IL-17A, which triggers not only skin lesions but also systemic inflammation and other psoriasis-associated comorbidities." (PMID 31622280, 2019). "IL-17A and IL-17F are significantly implicated in immune responses to infectious pathogens and in the pathogenesis of inflammatory autoimmune diseases like psoriasis." (PMID 32010143, 2019). "In an imiquimod-induced psoriasis model, AhR deficiency exacerbates skin inflammation with upregulated gene expression of Il22, Il17a, and Il23." (PMID 31683543, 2019). "This in turn led to the decreased IL-17A production in the skin and consequently reduced the severity of psoriasis in TIPE2-deficient mice." (PMID 31616442, 2019). "Within this family, IL-17A, IL-17C, and IL-17F are implicated in psoriasis pathogenesis as their expression is increased up to eightfold in psoriatic lesions." (PMID 30109481, 2018). "Th17 cells became thus the center of extensive research, and the hallmark cytokine IL-17A was identified as a novel key effector pathogenic factor in psoriasis." (PMID 30127781, 2018). "Elevated levels of IL-17A and the resulting cytokine release are linked to many autoimmune related diseases, including psoriasis, asthma, and rheumatoid arthritis." (PMID 29329326, 2018). "Elevated levels of IL-17 are a hallmark of psoriasis, therefore, rendering IL-17A inactive reduces inflammation." (PMID 29928283, 2018). "This, in turn, drives expansion of ADAMTS-like protein 5 (ADAMTSLP5), another psoriasis autoantigen, causing additional expression of IL-17A and IFN-γ." (PMID 30109481, 2018). "In both human psoriasis and murine models of psoriasiform inflammation, IL-23 is predominantly produced by myeloid DCs and promotes the expansion of pathogenic IL-17A-producing γδ T cells and CD4+ Th17 cells." (PMID 28469254, 2017). "The IL-17A concentration was higher in moderate to severe psoriasis, while higher IL-6 levels were associated with joint involvement and sporadic form of psoriasis." (PMID 28790368, 2017). "Increasing evidence implicates involvement of ILC3s in psoriasis, a skin inflammatory disease largely resulting from overproduction of Th17-associated cytokines such as IL-17A." (PMID 28271445, 2017). "The topical application of Aldara in mice deficient in IL-17A, IL-17F, or IL-22 drastically reduced the severity of psoriasis." (PMID 29249871, 2017). "Active IL-36 cytokines cooperated strongly with IL-17A in stimulating gene transcription, suggesting that an IL-17–IL-36 feed forward axis promotes and amplifies the inflammatory processes associated with psoriasis." (PMID 29142248, 2017). "The association between IL-17A and psoriasis is well established in humans, mouse and in vitro models." (PMID 28963556, 2017). "It has been shown that STAT3 is involved in the upregulation of keratin 17, a hallmark of psoriasis, in keratinocytes following IL-17A stimulation." (PMID 27711196, 2016).